TLR4 (toll like receptor 4)
Diseases named in the same sentence as TLR4 in open-access papers (continued):
Sharing a sentence is not in itself a finding about the gene and the disease.
infection (continued). "TLR4 acts as a critical factor in severity of AD in the presence of its ligand LPS-induced infections, and this alteration of TLR4 expression is consequential in the skin of AD." (PMID 34691014, 2021). "For example, toll-like receptor 4 (TLR4) is a basic receptor that recognizes LPS as a marker of infection." (PMID 34941684, 2021). "When Neu1 alone was overexpressed followed by infection, it led to the activation of the MyD88-pathway possibly due to TLR4-desialylation." (PMID 33763070, 2021). "The fold change of tlr4 was highest in the AA0 group (10.24-fold) at 24 h post-infection, and subsequently, the highest level declined to 3.55-fold in the AA5000 group at 6 h." (PMID 34573080, 2021). "Along the same line, LPS from E. coli, a very well-characterized TLR4 agonist, when administered 24 h before infection followed by 3 days post-infection, produced 100% survival." (PMID 35046936, 2021). "TLR4 forms complexes that lead to recruitment of members of IL1 receptor signaling to sites of infection." (PMID 33763112, 2021). "Amongst the several pathways of entry to the nervous system, we propose an alternative pathway from the infection of the gut, involving Toll-like receptor 4 (TLR4), zonulin, protease-activated receptor 2 (PAR2) and zonulin brain receptor." (PMID 33981312, 2021). "In mid-later stages of infection, however, the attenuated type I IFN signal by the NOD2 deficiency would be sufficiently compensated by the operation of other PRRs such as TLR2 and TLR4." (PMID 34777348, 2021). "To further confirm this dual regulation of TLR4 activation by Neu1/siglec-E, we separately overexpressed Neu1 and silenced siglec-E followed by infection." (PMID 33763070, 2021). "The gene expression levels of TLR4 and NF-κB were significantly upregulated after infection with A. hydrophila (P < 0.05), and AKG supplementation was associated with a significant downward trend of the gene expression levels of TLR4 (P < 0.05)." (PMID 34220849, 2021). "Following infection with bacteria, the TLR4/MD-2 complex triggers the initiation of down-stream signalling events, resulting in the translocation of transcription factors from the cytoplasm into the nucleus." (PMID 32033486, 2020). "Then, we showed a lower level of CXCL1 and CCL3 in TLR-2KO and TLR-4KO peritoneal lavage, suggesting that TLR-2 and TLR-4 are important to chemokine production by resident cells in the infection site." (PMID 33193308, 2020). "Our study demonstrated that infection of ExPEC XM O2:K1:H7 strain lead to up-regulation of TLR4 and induced COX-2 expression through the activation of p38 and the ERK1/2 MAPK pathway." (PMID 32362888, 2020). "TLR4 signaling seems to play an important role in the balance between the ability to control infections and in the pathogenesis of inflammatory diseases." (PMID 33138336, 2020). "Infection and inflammation of influenza A virus are inhibited on the basis of TLR4-MAPK p38 pathways." (PMID 32340172, 2020). "Concurrently, coordinated induction of the pro-inflammatory signaling via TLR4 and/or caspase-4/11 pathways is believed to mount an advantageous immune activation aimed at protection from infection and management of chronic inflammation." (PMID 33329561, 2020). "The TLR4–/–and MyD88–/– mice survived less time after infection than their corresponding WT animals (WT.BL10 and WT.BL6, respectively), although the TLR4–/– mice survived worse than the MyD88–/– mice at this CFU dose." (PMID 33042124, 2020). "The entrance of a pathogen into the trophoblast cell expressing TLR4, however, results in excessive chemokine secretion, which leads to enhanced chemotaxis of a monocyte and neutrophil to the site of infection." (PMID 32508811, 2020). "For these reasons, in our study, infection with 150 CFU of the Mtb K strain caused severely inflamed lesions and greater bacterial burden in TLR4-deficient mice than TLR4-expressing mice." (PMID 32403973, 2020).
infection (continued). "In the same way, infection with S. enterica resulted in increased hepcidin secretion, in agreement with our previous report suggesting that TLR-4 activation is responsible for hepcidin expression in macrophages during infection." (PMID 33290416, 2020). "Production of cytokines and chemokines that recruit neutrophils to sites of infection and injury is a pivotal contribution of Tlr‐4 signaling to innate immune defense against bacterial pathogens." (PMID 33030238, 2020). "In this context, DC-SIGN activation by ManLAM also modulates the TLR4-mediated NFκB signaling pathway and modifies the IL-10/IL-12p70 secretion balance in favor of IL-10 to promote the infection." (PMID 32722168, 2020). "A prominent pathway leading to NET formation in infection is through the interaction of lipopolysaccharide (LPS), with toll-like receptor 4 (TLR4) found on neutrophils." (PMID 32830308, 2020). "This led us to study a possible interaction between nicotine and TLR2/TLR4 in macrophages during infection." (PMID 33212859, 2020). "TLR-4 immune-related genes in neutrophils whose transcript levels exhibited twofold or greater modulation after infection with A. baumannii at 2h." (PMID 33253325, 2020). "We previously found that MAIR‐II expressed on inflammatory monocytes regulates lipopolysaccharide‐TLR4–mediated cell adhesion to vascular cell adhesion molecule 1, promoting monocyte migration to sites of infection." (PMID 33140535, 2020). "The release of fungal proteases during infection has been reported to result in fibrinogen cleaving and activation of the TLR4 signaling pathway through binding of fibrinogen cleavage products." (PMID 33043780, 2020). "The LPS-induced activation of TLR4 often leads to the production of multiple cytokines to protect against infection." (PMID 32432106, 2020). "Here, we observed that inhibition of both TLR2 and TLR4 signaling with OxPAPC resulted in significantly higher retained retinal function after infection with the WT strain, likely due to the preserved retinal architecture in these eyes." (PMID 32117322, 2020). "High levels of Tlr4 messenger RNA (mRNA) expression were detected initially after 48 h of infection and later at 4 and 6 weeks post-infection (wpi), in the spleen." (PMID 32210480, 2020). "First, we detected TLR4 expression at 3, 6, and 12 h post infection (hpi), the receptor involved in the LPS response." (PMID 32269560, 2020). "Differentiated THP-1 cells were exposed to either 20 μg/ml of TLR4-ab or an IgG isotype control prior to infection by Bt and subsequent treatment with lactoferrin." (PMID 32764765, 2020). "Gene expression analyses demonstrated that IRF1 and IFN-β were expressed downstream of TLR4 after infection." (PMID 32210480, 2020). "The respiratory burst (ROS production) after infection was profoundly dampened in TLR4–/– and MyD88–/– mice." (PMID 33042124, 2020). "When wild-type mice were treated with TAK-242, a potent inhibitor of TLR4 signaling, and subsequently challenged with intraperitoneal LPS injection alone, LPS infection-induced mortality and elevation of proinflammatory cytokines were profoundly inhibited." (PMID 33042141, 2020). "The activation of RAW 264.7 cells induced by TLR2 and TLR4 agonists favored the phagocytosis of C. gattii and inhibited the growth of yeast in the early period of infection." (PMID 33304649, 2020). "During infection, stimulation of Toll-like receptor 4 (TLR4) by lipopolysaccharide (LPS) from the outer membrane of gram-negative bacteria induces hematopoietic cells, particularly macrophages, to express a variety of pro-inflammatory cytokines." (PMID 32027657, 2020). "In that study, all wild-type mice died of the infection whereas all TLR4-/- mice survived, despite the comparable tissue bacterial burdens between the two strains of mice." (PMID 33042864, 2020).
infection (continued). "The PGE2 production is directly connected to pathogen induced toll like receptor-4 (TLR4) signaling and therefore, delineates the connection of infection induced LN reactivity with angiogenic vessel formation." (PMID 33343570, 2020). "Tenascin-C (TNC) is an extracellular matrix protein rapidly induced at the site of infection or injury, where it triggers inflammation by activating TLR4 in different cells, including macrophages." (PMID 32209460, 2020). "As a consequence of host infection with S. Typhimurium, its outer membrane structure (LPS) can trigger an immune cytokine storm through the pattern recognition receptor, TLR4." (PMID 33363324, 2020). "The avirulent S. Typhimurium ∆rfa mutants are potentially useful for modulation of the TLR2 and TLR4 signaling pathways to protect the immunocompromised gnotobiotic piglets against subsequent infection with the virulent S. Typhimurium." (PMID 32842482, 2020). "In the liver, tlr4 expression largely occurred in only the chronic stage of infection, starting at 3 wpi and remaining high up to 6 wpi." (PMID 32210480, 2020). "Compared to Sigirr−/− counterparts, TLR-4 deficient Sigirr−/− animals displayed less TNF-α and IFN-γ expression in ceca upon infection, which was comparable to that assessed in uninfected control mice." (PMID 32231139, 2020). "The high TLR4 expression is important to improve the infection response, however the continuous expression leads to a release of pro-inflammatory cytokines." (PMID 31924826, 2020). "Then, pro-inflammatory immune response induced in RAW 264.7 cells by TLR2 and TLR4 agonists favors the uptake of C. gattii promoting a control of growth of yeast in the early stage of infection." (PMID 33304649, 2020). "CPE reduced the mRNA level of TLR4, MyD88, and AP-1 exerted anti-inflammatory effects, and simultaneously resistance LPS infection to stimulus." (PMID 32581806, 2020). "We observed that the delayed kinetics of IFN-β expression (at 3 wpi) affected the TLR4-mediated impact on DCs, interfering with the Th1 response and parasite control during the chronic phases of infection." (PMID 32210480, 2020). "It is known that necroptosis can be initiated by activation of TLR3 or TLR4 as well as pathogen infection in addition to activation of death receptors." (PMID 33364238, 2020). "TLR4 expression is upregulated by infection, in part due to infiltration of TLR4‐expressing leucocytes in tissues." (PMID 32313651, 2020). "According to these results, TLR4 plays an important role in the activation of DCs during an hMPV infection." (PMID 32765522, 2020). "LPS infection induces TLR4 expression to disturb the TJ integrity and elicits inflammatory response." (PMID 31949265, 2020). "Fourteen-day infection with S. Typhimurium in these pigs increased the relative expression of TLR4 and TLR9 mRNA in the ileum." (PMID 32842482, 2020). "A previous study showed that TLR2 and TLR4 were expressed in tissue infected with Nocardia during the early stages of infection." (PMID 31964749, 2020). "We found that infection with the wild-type S. Typhimurium upregulated mRNA in the terminal ileum in all analyzed members of the TLR4 signaling pathway—TLR4, MD-2, CD14, and LBP." (PMID 32842482, 2020). "TLR4-deficient IL10-/- mice, however, displayed less severe clinical signs of infection, that were accompanied by less distinct apoptotic epithelial cell and innate as well as adaptive immune cell responses in the colon, as compared to IL10-/- counterparts." (PMID 32443576, 2020). "This modification increases the Toll-like receptor 4(TLR4)/myeloid differentiation factor 2 (MD-2)-mediated innate immune recognition of these pathogens during infection." (PMID 33322274, 2020). "Because the ex vivo expression of these receptors was higher on inflammatory monocytes from CL patients, further experiments evaluating the expression of TLR2 and TLR4 on monocyte subsets after infection with L. braziliensis were performed." (PMID 31119102, 2019).
infection (continued). "TLR4−/− mice show reduced survival upon infection with increased bacterial loads in lungs and bronchopneumonia." (PMID 30452654, 2019). "Antibiotic and synbiotic supplementation had significant effects on cecal tonsil TLR-4 mRNA content at 3 (P < 0.01), 7 (P < 0.01), 14 (P <0.01) and 21 (P < 0.01) d post-infection." (PMID 31600299, 2019). "E. faecium upregulated the mRNA expression of PPAR-γ and IL-10 (P < 0.05) and downregulated that of NF-κB, TLR4, and IL-1β (P < 0.05) in the spleen 3 and 7 days post-infection." (PMID 29948799, 2019). "During infection, toll-like receptor 4 (TLR4) and toll-like receptor 2 (TLR2) recognize gonococcal PAMPs and consequently activate the downstream inflammatory signaling cascade in immune cells." (PMID 31417575, 2019). "Here, we show that the microbiota regulates microglia function through TLR4, priming these cells to respond to infection." (PMID 31309928, 2019). "In TLR4−/− knockout mice, gene expression of the GRO encoding gene was significantly reduced after infection with B. cereus, supporting the role of TLR4 receptor in the expression of GRO in response to bacterial infections." (PMID 31131263, 2019). "So far, these results indicate that in human CL, in addition to TLR2 and TLR4 are preferentially expressed in intermediate monocytes, the infection with L. braziliensis increases the expression of these receptors on this monocyte subset." (PMID 31119102, 2019). "For example, hypoacylation of lipid A occurs when Y. pestis is growing at 37°C, and this form of lipopolysaccharide (LPS) appears to antagonize TLR4, minimizing its role in defense against infection." (PMID 30642901, 2019). "To better assess the relation between TLR4 and H. pylori, we decided to study its expression in the WBCs of a subsample of individuals who were stratified according to their infection status." (PMID 30641993, 2019). "At Day 3 post-infection in the footpad, CD11b+ DCs from CD11ccreIL-4Rα−/lox and littermate control mice expressed equivalent levels of TLR4 and TLR9." (PMID 32039054, 2019). "This premise can now be interrogated by assessing the susceptibility of anti-FBG treated animals to infection, and by comparison of the efficacy and safety profiles of anti-FBG and anti-TLR4 antibodies." (PMID 30552174, 2019). "Of TLRs, we focused on TLR2 and TLR4 due to their ability to mediate inflammation not only at the interaction of bacteria with endometrial cells during infection, but also at the interaction of sperm with cumulus-oocyte complexes during fertilization." (PMID 30995239, 2019). "TLR4 knockout mice have reduced inflammation and impaired bacterial clearance during NTHi infection, further supporting a role for neutrophils in the eradication NTHi." (PMID 31417543, 2019). "TLR4 plays an important role in various infection-induced inflammatory responses, and participates in various cellular functions." (PMID 31358689, 2019). "In our experiments, IL-10-producing B cells induced after C. muridarum stimulation exhibited innate-like B cell characteristics since they were rapidly induced during the course of the infection and depended on TLR4 signaling." (PMID 30881362, 2019). "Given the importance of MIC1 and MIC4 as lectins that engage TLR2 and TLR4 N-glycans to induce increased levels of IL-12 release during T. gondii in vitro infection, we investigated the biological relevance of these proteins during in vivo infection." (PMID 31226171, 2019). "Accordingly, our main objective was to explore how and why TLR4 functioning is hampered during initial phase of infection with promastigotes which are the infective form of the parasite and encounters the host defense mechanism." (PMID 31649671, 2019). "After TLR4 recognizes LPS infection, it initiates immune reactions to try to clear up the infection, for instance by promoting the production of proinflammatory cytokines and mediating infiltration and activation of inflammatory cells." (PMID 30915370, 2019).
infection (continued). "The expression of TNF-α, IL-12p70, and IL-10 was induced by MAH-infected DCs exposed to LPS in the same manner as LPS-alone treatment in TLR2−/− and as MAH-alone infection in TLR4−/−." (PMID 31440223, 2019). "The S100A8/A9 complex also protects the host from infection by triggering toll-like receptor 4 (TLR4) and receptor for advanced glycation end-products (RAGE)-mediated inflammatory pathways, and through the recruitment of neutrophils." (PMID 31619666, 2019). "The majority of the C3H/HeJ animals and all of the TLR4-knockout animals expired from pbgA-lpxC infections within roughly 1 week." (PMID 31611279, 2019). "This suggests that the mechanism involves the regulation of TLR4 expression by IL-2, which then regulates the content of IgA in the urinary space, preventing the establishment of infection." (PMID 31911807, 2019). "The aim of this study was to determine the expression of TLR2 and TLR4 in the eyes of mice following intranasal infection with Acanthamoeba spp." (PMID 31309100, 2019). "For example, eritoran, a TLR4 antagonist, is protective when administered starting on 2 days post-infection, but only has limited effects when given 3 h prior to infection." (PMID 31293574, 2019). "TLR4 deficiency increases mortality and reduces bacteria clearance after an infection, so TLR4 function plays a critical role for the immune response during bacterial infection." (PMID 31480668, 2019). "At 21 d post-infection, birds in the antibiotic and synbiotic supplementation group had 70, and 56% decreased TLR-4 mRNA compared to the control group, respectively." (PMID 31600299, 2019). "We observed decreased sialylation of TLR4 in the Neu1-transfected cells compared to mock transfection during infection." (PMID 31649671, 2019). "TLR4 has a controlling role in infection with L. major whose increase of expression reduces the lesion." (PMID 31057724, 2019). "We also evaluated the expression of TLR2 and TLR4 on monocytes from HS after infection with L.braziliensis." (PMID 31119102, 2019). "Studies have shown that TLR4-dependent IL-12 productions play crucial roles in promoting DC maturation and the pro-inflammatory immune response to eliminate pathogens from the infection." (PMID 31337442, 2019). "Previous studies have used LPS stimulus to induce changes in NF-kappa B activation and Toll-like receptor 4 signalling pathways, simulating the exaggerated host response to infection through the release of adhesion molecules and cytokines." (PMID 31827375, 2019). "In vitro infection with L. braziliensis caused CL monocytes to up-regulate TLR2 and TLR4 expression." (PMID 31119102, 2019). "On the other hand, the CL-Brener strain infection induced a lower expression of TLR4+ BMDCs compared to the INC5 and Ninoa strains (p = 0.0004 for BALB/c and p = 0.01 for C57BL/6)." (PMID 31636507, 2019). "All these findings suggest that infection after Neu1 overexpression leads to TLR4 activation through its desialylation." (PMID 31649671, 2019). "TLR4 to nuclear factor-kappa B (TLR4-NF-κB) pathway is involved in pathogen identification and infection defense in mammals." (PMID 31031640, 2019). "Instead, inflammasome activation was induced during the late stage of infection using the classical priming TLR4 agonist LPS and the inflammasome activator ATP." (PMID 31849970, 2019). "Here, we argue that responses mediated by Toll-like receptors (TLRs), particularly TLR4, have a decisive impact on the development of placental pathologies during infection." (PMID 31178840, 2019). "Although it has not been extensively studied, it is possible that TLR4 is also involved in the recognition of bRSV, as in vitro infection of bovine TLR4 transfected cells induces TLR4-dependent NF-κB response." (PMID 30626099, 2019). "As we know, the LPS receptor TLR4 is a central player in signaling pathways of the innate immune response to infection by pathogen." (PMID 30979040, 2019).